KLF7 (KLF transcription factor 7)
Diseases named in the same sentence as KLF7 in open-access papers (continued):
Sharing a sentence is not in itself a finding about the gene and the disease.
tumor (continued). "Importantly, based on our data for 7 Ba/Sq samples, we were able to identify higher enhancer activity associated with potential key genes in Basal tumour biology, including cell surface receptors (IL7R, OSMR, EGFR, MET) and transcriptional regulators (BNC2, HMGA2, KLF7, NR3C1)." (PMID 36944729, 2023). "To identify whether circUBE2J2 exerts its biological functions through the miR-370-5P/KLF7 axis, we performed rescue experiments using miR-370-5p inhibitors to detect whether the tumor-promoting effect of knocking down circUBE2J2 could be blocked by inhibiting miR-370-5p." (PMID 34686662, 2021). "Therefore, KLF7 upregulation of HAS2 contributes to UCEC tumor growth." (PMID 33892667, 2021). "In addition, compared with NC mimic + NC, miR-450b-3p expression dramatically increased in the tumor tissues of nude mice with miR-450b-3p mimic + NC by qRT-PCR; However, overexpression of KLF7 could decreased the level of miR-450b-3p." (PMID 32063748, 2020). "In these samples, both KLF7 and PDGFB exhibited up-regulation in tumor tissues compared to adjacent normal tissues." (PMID 38164176, 2024). "Furthermore, we found that in the shKLF7 plus DT group (shKLF7 + DT) showed a significantly increased tumour size, volume, and weight compared to the shKLF7 group (shKLF7 + Vehicle), revealing that DT could restore the tumour suppressive effect of KLF7 knockdown on the progression of HCC." (PMID 39648156, 2024). "Representative IHC staining of KLF7, TLR4, and PTK2 in HCC tissues and adjacent non-tumor tissues is presented." (PMID 37554278, 2023). "Compared to para-tumor specimens, the mRNA levels of KLF5, KLF7, KLF8, and KLF13 were elevated, whereas those of KLF4, KLF6, and KLF10 were reduced in HCC specimens." (PMID 37554278, 2023). "A recent study reported that KLF7 is up-regulated in human HCC and enhances tumor proliferation and invasion." (PMID 37554278, 2023). "We also identified genes encoding membrane receptors (IL7R, OSMR, EGFR) and transcriptional regulators (BNC2, BNC1, HMGA2, KLF7, NR3C1) as enriched in Basal tumours." (PMID 36944729, 2023). "Knockdown of KLF7 inhibits the expression of IFN-stimulated genes, which are necessary for KLF7-mediated PDAC tumor growth and metastasis." (PMID 34686662, 2021). "The results showed that both KLF7 and HAS2 were downregualted in shKLF7 tumor tissues as compared shCtrl tissues." (PMID 33892667, 2021). "Lastly, knockdown of HAS2 reversed the oncogenic role of KLF7 on UCEC cell proliferation, migration, and xenografted tumor development." (PMID 33892667, 2021). "More importantly, the role of KLF7 in driving EMT by regulating Vimentin levels, was also confirmed in the spheroid models, these latter more closely resembling the in vivo tumour growth situation." (PMID 33250051, 2020). "Genes such as CFLAR, EP300, GBP2, HEYL, KLF7, NOTCH1 or POFUT showed a similar correlation with NUMB or NUMBL in the three tumor types considered." (PMID 29507685, 2018). "To determine whether KLF7 promotes HCC tumorigenesis through Trp metabolism, we established a tumour xenograft model." (PMID 39648156, 2024). "Importantly, we also identified a Basal TF network, including ZBED2, KLF7, HMGA2, and NR3C1 as major regulators, whose expression was restricted to the basal component of tumours, according to scRNA-seq data." (PMID 36944729, 2023). "Interestingly, KLFs can exert opposite effects in regulating the same pathways and initiate different cell responses, as some of them can function as tumor suppressors (KLF2, KLF8) and some as oncogenes (KLF7, KLF9)." (PMID 37239940, 2023). "First, we found that the expression level of KLF7 is higher in PCa tissues of patients, and the expression of KLF7 is positively correlated with tumour-promoting gene IL-6, while it is negative correlated with another tumour-suppressor gene p21." (PMID 37170248, 2023).
tumor (continued). "The expression level of serum KLF7 was not related to gender, age, smoking history, and tumor diameter of NSCLC patients (P > 0.05), but related to the degree of differentiation and TNM stage of NSCLC patients (P < 0.05)." (PMID 35936369, 2022). "The expression level of serum KLF7 was not related to gender, age, smoking history, and tumor diameter of NSCLC patients (P > 0.05) but significantly related to the degree of differentiation and TNM stage of NSCLC patients (P < 0.05)." (PMID 35936369, 2022). "MiR-3666/KLF7 axis, as the downstream target of KCNQ1OT1, regulate tumor growth." (PMID 36545680, 2022). "Also, KLF7 expression is activated in PDAC, and it leads to the induction of release of tumor-driver cytokines and PDAC cell expansion and development." (PMID 34659523, 2021). "Moreover, KLF7-positive patients exhibited a higher incidence of absent tumor encapsulation, microvascular invasion, poor tumor differentiation, and advanced tumor-node-metastasis (TNM) stage." (PMID 37554278, 2023). "After the establishment of xenografts tumors, tumor growth and weights were both found to be lower in the LV-sh-LINC00152+LV-oe-NC than those in the LV-sh-NC+LV-oe-NC group, but higher in the LV-sh-LINC00152+LV-oe-KLF7 group than those in the LV-sh-NC+LV-oe-NC group." (PMID 34659523, 2021). "Additionally, miR-450b-3p and KLF7 expression presented a significant negative correlation in GC tumor tissues." (PMID 32063748, 2020).
cancer (21 papers, 2015 to 2025). A tumor composed of atypical neoplastic, often pleomorphic cells that invade other tissues. "Differentially expressed genes (DEG) were selected (|log2FC|≥1, P<0.05), and their enriched signaling pathways were identified, showing that KLF7 regulated several signaling pathways associated with cancer, including MAPK/ERK, RAS, JAK/STAT3, and PI3K/AKT." (PMID 38164176, 2024). "Our RNA-seq data revealed that KLF7 is linked with several cancer signaling pathways, such as PI3K/AKT, JAK/STAT3, and MAPK/ERK in COAD." (PMID 38164176, 2024). "Furthermore, several studies have implicated KLF7 in the regulation of critical pathways involved in cancer progression." (PMID 38116138, 2023). "Additionally, patients with high KLF7 expression had a significantly elevated risk of cancer-specific mortality compared to those with low KLF7 expression (HR = 2.597, 95% CI: 1.070-6.301, P = 0.035)." (PMID 38116138, 2023). "IHC staining revealed that the cancer cell proliferation was significantly suppressed in the KLF7 stable knockdown group, as indicated by decreased Ki-67 staining." (PMID 38164176, 2024). "The transcriptional activator KLF7 is abnormally expressed in multiple cancers, including pancreatic, endometrial, lung, liver, gastric, breast, and prostate cancers." (PMID 38164176, 2024). "We enrolled 57 CRC patients who underwent surgery in our hospital and tested KLF7 expression in cancer tissues and adjacent tissues." (PMID 39097779, 2024). "MSCs deliver miR‐204 via exosomes and target Krüppel‐like factor 7 (KLF7) within the KLF7/AKT/HIF‐1α axis to inhibit EMT in cancer." (PMID 39247621, 2024). "Among them, KLF7 is up-regulated in various cancer tissues, can act as an oncogene to promote the proliferation and metastasis of cancer cells." (PMID 37170248, 2023). "The transcription factor Krüppel-like factor 7 (KLF7) has increasingly attracted attention in the context of cancer development." (PMID 36192788, 2022). "We showed that KLF7 was strongly expressed in cancer tissues, in which the cell nucleus was stained with KLF7 antibody." (PMID 33858520, 2021). "Overall, KLF7 functions as on oncogene in different cancers and its upregulation can be regulated by various factors." (PMID 33892667, 2021). "Krüppel-like factor 7 (KLF7) acts as an oncogene in various cancer types, whereas the connection between GNA14 and KLF7 in UCEC is unclear." (PMID 33892667, 2021). "Based on their transcription activity, KLF7 regulates the expression of various genes and participates in cancer development." (PMID 33892667, 2021). "More recently, however, new evidence have become available suggesting a role for KLF7 in cancer development and progression." (PMID 33250051, 2020). "As a first step in the investigation of the role of KLF7 in cancer development, we assessed protein expression in a panel of cell lines selected among those considered as really representative of HGSOC." (PMID 33250051, 2020). "Mechanistic targets of KLF7 included genes involved in epithelial to mesenchymal transition, and in maintaining pluripotency and self-renewal characteristics of cancer stem cells." (PMID 33250051, 2020). "Accordingly, functional in vitro experiments demonstrated that KLF7 promotes proliferation, migration and invasion in different cancer cell lines." (PMID 33250051, 2020). "KLF7 can also enhance cancer cell migration, and invasion across various cancer types." (PMID 40316546, 2025). "KLF7 showed a high expression pattern in cancer tissues (p < .01)." (PMID 39097779, 2024).
cancer (continued). "qRT-PCR results suggested that KLF7 was overexpressed in the cancer tissues." (PMID 33858520, 2021). "As a transcription factor, KLF7 participates in the development of various cancers." (PMID 33892667, 2021). "Dysregulation of KLF7 participates in the development of various cancers, but it is unclear whether there is a link between HCC and aberrant expression of KLF7." (PMID 33858520, 2021). "However, while other members in the family have been broadly characterized for their functions in various cancer-relevant processes, mechanistic insights relative to KLF7 role in cancer pathogenesis are very limited." (PMID 33250051, 2020). "Interestingly, KLF7 has been shown to modulate stem cells and lineage differentiation, but if KLF7 likewise influences cancer stem cells and how this may relate to colon tumorigenesis remains to be studied." (PMID 36890812, 2023). "KLF7 might therefore play an important role in cancer progression." (PMID 36192788, 2022). "Recent studies have shown that KLF7 is also involved in many new biological processes, such as sciatic nerve regeneration, mediating tissue inflammatory response, participating in cancer radiotherapy and chemotherapy rehabilitation, regulating oxidative phosphorylation pathway, and so on." (PMID 35936369, 2022). "KLF7 was predominantly localized in the nucleus and showed markedly elevated intensity in HCC tissues compared to para-cancer tissues." (PMID 37554278, 2023). "Then, we performed IHC staining of KLF7 in HCC tissue microarray, which contained 50 cancer tissues and 20 normal tissues." (PMID 33858520, 2021). "Actually, There are growing evidence revealing that KLF7 is aberrantly expressed in a variety of human solid tumors and plays pivotal roles in proliferation, migration, invasion and EMT, poor prognosis of cancer cell lines." (PMID 33858520, 2021). "Overall, the available literature and our data support the idea that KLF7 oncogenic activity may progress via different pathways, mainly affecting the EMT-program and cancer stemness." (PMID 33250051, 2020). "The research shows that the research on KLF7 in the serum of cancer patients is not uncommon." (PMID 35936369, 2022). "The research on KLF7 in the serum of cancer patients is not uncommon." (PMID 35936369, 2022).
infection (3 papers, 2017 to 2024). The state of being infected such as from the introduction of a foreign agent such as serum, vaccine, antigenic substance or organism. "Infection of NMCMs with lentivirus containing sh-Klf7 increased the mRNA and protein expression of hypertrophy-related genes with and without AngII stimulation." (PMID 36810848, 2023). "As NGF and TrkA are considered downstream targets of KLF7, these results suggested a successful and functional induction of KLF7 by AAV2 infection in spinal cord neurons in vitro." (PMID 28884027, 2017).
neurodevelopmental disorder (3 papers, 2017 to 2025). A behavioral and cognitive disorder with onset during the developmental period that involves impaired or aberrant development of intellectual, motor, or social functions. "This study provides mechanistic insights into the neurological deficits associated with KLF7 pathogenic variants and highlights potential therapeutic targets for neurodevelopmental disorders." (PMID 40762575, 2025).
cardiovascular diseases (2 papers, 2023 to 2024). "KLF7's involvement in various cardiovascular diseases is well-documented." (PMID 38511055, 2024).
metabolic disease (2 papers, 2018 to 2024). A congenital disorder (due to inherited enzyme abnormality) or acquired (due to failure of a metabolically important organ) disorder resulting from an abnormal metabolic process. "The current findings highlight the importance of exploring the role of RES in the regulation of KLF7 and HIF1A expression and its potential implications for managing inflammatory diseases and metabolic disorders." (PMID 38212345, 2024).
psychiatric disorder (2 papers, 2023 to 2024). A disorder characterized by behavioral and/or psychological abnormalities, often accompanied by physical symptoms. "KLF7 are also found to be associated with several psychiatric disorders, including ASD, MDD and sleep problems." (PMID 37658396, 2023).
KLF7 also shares sentences with these, for which no sentence is quoted: endometrial cancer (4 papers); cervical cancer (2); esophageal squamous cell carcinoma (2); lymph node metastasis (2); metabolic syndrome (2); oral cancer (2); acute myeloid leukemia (1); adenocarcinoma (1); Ataxia (1); autoimmune disease (1); autosomal dominant disease (1); blood disease (1); Colon (1); depression (1); diabetic cardiomyopathy (1); epilepsy (1); gallbladder carcinoma (1); glioblastoma (1); glucose metabolism (1); hypertrophic cardiomyopathy (1); hypoplastic left heart syndrome (1); memory impairment (1); metastasis (1); microcephaly (1); schizophrenia (1); serous ovarian cancer (1); spinal cord injury (1); Stroke (1); Tetralogy of Fallot (1).